INS (insulin)
Diseases named in the same sentence as INS in open-access papers (continued):
Sharing a sentence is not in itself a finding about the gene and the disease.
lipodystrophy (continued). "In subcutaneous fat, 30 genes compared to 10 genes in the visceral fat showed a positive correlation with HOMA-B, pointing toward a possible relation of insulin secretion with these lipodystrophy genes." (PMID 39444451, 2024). "Our findings align with the existing literature on pregnancy and lipodystrophy, indicating increased insulin resistance, metabolic changes, and a higher prevalence of fetal complications." (PMID 38633761, 2024). "Clinical studies have demonstrated the sustained efficacy of metreleptin in lipodystrophy, characterized by improvements in insulin resistance, glycemic parameters, lipid abnormalities, and hepatic fat accumulation." (PMID 38992753, 2024). "The patient in this case reported using the same insulin needle for up to two weeks and failing to rotate injection sites due to convenience and discomfort, which likely contributed to the development of lipodystrophy." (PMID 39759721, 2024). "This case highlights the important relation between insulin-induced lipodystrophy and its psychological impact." (PMID 39759721, 2024). "This case highlights the importance of addressing the psychological aspects of insulin-induced lipodystrophy." (PMID 39759721, 2024). "Various studies have shown low levels of testosterone correlate not only with central fat accumulation but also with higher insulin levels which suggest testosterone also has an effect in insulin sensitivity in HIV-lipodystrophy." (PMID 38654196, 2024). "Several factors influencing glycemic variability in children and adolescents with T1D have been identified, including physical activity, pubertal status, meal composition, irregular sleep patterns, and the presence of insulin-induced lipodystrophies." (PMID 38397323, 2024). "A multidisciplinary approach is essential to ensure that both the physical and psychological needs of patients with insulin-induced lipodystrophy are addressed." (PMID 39759721, 2024). "We found that inguinal fat in PpargC/- mice with partial lipodystrophy exhibited increased insulin sensitivity and preserved adipose tissue flexibility, despite significant decreases in these in perigonadal fat." (PMID 36835312, 2023). "HFDTZD-fed PpargC/- mice showed similar insulin-induced Akt phosphorylation in both perigonadal and inguinal fat, suggesting that TZD is effective in correcting insulin sensitivity of fat depots in mice with partial lipodystrophy." (PMID 36835312, 2023). "Lipodystrophy was also observed at the insulin injection site under two aspects, lipoatrophy and lipohypertrophy." (PMID 37600771, 2023). "It is therefore now possible to compare various infusion parameters such as basal rate, CSII model, cannula length, material, infusion site, lipodystrophy, on insulin spread in the SC tissue." (PMID 37973963, 2023). "To evaluate the response of TZD to different depots in mice with lipodystrophy, we compared insulin-induced Akt phosphorylation in perigonadal and inguinal fat with or without TZD treatment." (PMID 36835312, 2023). "In order to enhance the patient’s insulin injection technique to heal lipodystrophy, improve psychological indices, and promote involvement in their health and care, the efficacy of emerging person-centered care called the IARA model was tested." (PMID 36579585, 2022). "We observed remarkably similar alterations in the circulating parameters of cohorts representing PLWH with lipodystrophy and elderly individuals, including mild increases in insulin resistance and increased levels of proinflammatory cytokines and FGF21." (PMID 35300561, 2022). "Regarding symptoms and signs of complications from inadequate insulin application,clinical examination (inspection and palpation) showed a high frequency of tissuecomplications (73.5%), among which bruises, along with lipodystrophy (42.0%), werehighlighted." (PMID 35112702, 2022).
lipodystrophy (continued). "The forum reported that lipodystrophy, particularly lipohypertrophy, is a typical issue at injection sites when insulin is given repeatedly in the same location." (PMID 35854336, 2022). "Lipodystrophy is one of the most frequent complications in people with DM following subcutaneous insulin therapy, and poor management can lead to several problems, the most important of which is impaired glycemic control among patients." (PMID 36579585, 2022). "When Perilipin-1 deficiency is produced under a pure C57/Bl6 background, the mice similarly display partial lipodystrophy but a more marked insulin resistance along with strong macrophage inflammation in WAT is observed." (PMID 35250856, 2022). "On top of this, strategizing mechanisms to sustain insulin supply and taking measures to reduce development of lipodystrophy shall also be considered." (PMID 35705956, 2022). "Our findings confirm that failure to rotate insulin injection sites is closely related to the occurrence of lipodystrophy, as already demonstrated by previous studies." (PMID 35884071, 2022). "The study showed that the amount of time insulin had been used, the frequency of changing injection sites, and the frequency of changing needles can dramatically influence the development of lipodystrophy." (PMID 36579585, 2022). "These subgroups include insulin production- and secretion-related clusters deemed “proinsulin” and “β-cell” clusters, as well as “obesity,” “lipodystrophy,” and “liver/lipid” clusters." (PMID 35292083, 2022). "Due to the reduced vascularization and capillary density of the localized lipodystrophy, insulin is absorbed in a variable and unpredictable way." (PMID 36579585, 2022). "Although lipodystrophy might be specific for acquired or congenital loss of adipose tissue, more and more evidence supported that within lean people in the general population, some features of lipodystrophy exist, i.e., insulin resistance and accumulation of lipids in the liver." (PMID 34578806, 2021). "Consistently, tall stature has been described in patients with lipodystrophy who exhibit low levels of leptin and high levels of insulin." (PMID 34002033, 2021). "Fasting insulin was significantly higher in patients with insulin signaling defects than in those with lipodystrophy or idiopathic SIR." (PMID 33901270, 2021). "Akt2-coupled lipodystrophy, described in one family, is due to an autosomal dominant mutation in AKT2, a central protein in the insulin-mediated signalling cascade." (PMID 33233602, 2020). "Metreleptin, a recombinant analogue of human leptin, is the only specific therapy available for the management of human lipodystrophies that improve insulin sensitivity." (PMID 33233602, 2020). "A key feature of lipodystrophy is a drastic reduction in the levels of adipocyte-derived hormones including leptin, which is a major regulator of appetite, insulin sensitivity, and liver function." (PMID 31656583, 2019). "The frequency of DKA is significantly greater in T1DM adolescents with a higher HbA1c level, lipodystrophy and those who had discontinued insulin treatment." (PMID 31824422, 2019). "One (3.33%) patient had lipodystrophy who was on insulin treatment for past 5 years and 3 (10%) patients had local site reactions." (PMID 30069184, 2018). "Lipodystrophy is one of the clinical complications of insulin injection that affects insulin absorption and leads to poor glycemic control." (PMID 30116742, 2018). "The HOMA-β and AUCi values, obtained by patients with lipodystrophy, prove inadequate insulin secretion capacity." (PMID 29449893, 2018). "The PKB/Akt pathway has previously been shown to be targeted by ART; for example, HAART-treated HIV-infected participants with signs of lipodystrophy showed impaired insulin signalling in skeletal muscle at the level of PKB/Akt." (PMID 30517206, 2018).
lipodystrophy (continued). "SKO mice did not display significant differences in body weight but developed lipodystrophy, glucose intolerance, and insulin insensitivity, phenocopying previously reported seipin knockout models." (PMID 29459250, 2018). "Under conditions such as lipodystrophy, the lipolysis is enhanced, and prolonged fatty-acid exposure in β cells can decrease glucose-induced insulin secretion, impair insulin gene expression, and increase cell death." (PMID 28249577, 2017). "The characteristics of these mice are: lipodystrophy, organomegaly, decreased leptin and adiponectin in plasma, insulin resistance, elevated free fatty acids (FFAs) and hypotension." (PMID 27483259, 2016). "The PPARγldi/+ mouse show reduced fat mass and insulin sensitivity giving a unique model of human conditional lipodystrophy." (PMID 27483259, 2016). "Recent research publications have reported the use of two lipid-lowering class of drugs, statins and fibrates, antiretroviral switching strategies and use of insulin-sensitizing drugs in the management of the HIV lipodystrophy." (PMID 26789842, 2016). "In our sample, patients with lipodystrophy had higher glucose and insulin at 0 and 120 minutes on OGTT, and greater HOMA than patients without lipodystrophy." (PMID 24958511, 2014). "Another study has demonstrated that patients with severe lipodystrophy are sternly insulin resistant, which can be attributed to defects in insulin action in both liver and muscle." (PMID 24386337, 2013). "HIV-infected patients with lipodystrophy have decreased insulin-stimulated glucose uptake in skeletal muscle and defects in insulin-stimulated phosphorylation of Aktthr308." (PMID 24303139, 2013). "As the patient was the only known case of lipodystrophy in the family nothing remained but analyzing a possible defect in insulin signaling, we characterized known signaling pathways." (PMID 23919306, 2013). "Injection site rotation and disposing single use disposable syringe needles is an important component of insulin administration and is helpful in preventing lipodystrophy and achieving glycemic goal." (PMID 23620789, 2013). "On the other hand, subject 1 had severe signs of lipodystrophy in the insulin injection sites, problably related to the local deposit of immunocomplexes." (PMID 24386337, 2013). "Human immunodeficiency virus (HIV)-infected patients with lipodystrophy have decreased insulin-stimulated glucose uptake." (PMID 24303139, 2013). "In conclusion, we have shown that insulin-resistant HIV-infected patients with lipodystrophy have reduced basal and insulin-stimulated GS activity (%FV) as well as impaired insulin-stimulated Aktthr308 phosphorylation compared to HIV-negative controls." (PMID 24303139, 2013). "HIV-infected patients with lipodystrophy had been found to have a lower PPARγ level in the subcutaneous adipose tissue, and a higher waist-to-hip ratio, higher serum insulin and triglyceride levels." (PMID 23145084, 2012). "Deregulation in the production of these two adipocytokines has been observed in both obese and lipodystrophy states and has been proposed to contribute to the impairment of insulin sensitivity." (PMID 20180981, 2010). "In the present study, we investigated the effects of leptin infusion on insulin sensitivity and lipid metabolism in diet-induced lipodystrophy model mice." (PMID 18348717, 2008). "Inhibition of peripheral lipolysis improves insulin sensitivity in protease inhibitor-treated men with signs of lipodystrophy." (PMID 17597538, 2007). "Indeed, IL‐18 seems to be related to fat mobilization since patients with lipodystrophy treated with acipimox and insulin have reduced plasma concentrations of IL‐18." (PMID 41508774, 2026). "siRNA designed to restore AKT2 function could enhance both adipogenesis and insulin sensitivity, which is crucial for managing the metabolic aspects of lipodystrophy." (PMID 39944202, 2025).
lipodystrophy (continued). "Mouse models often show rapid liver lipid accumulation under HFDs, leading to pronounced lipodystrophy, whereas in humans, hepatic lipid accumulation occurs more gradually and is influenced by factors such as insulin resistance and subcutaneous fat storage capacity." (PMID 39948368, 2025). "In patients with lipodystrophies, metformin improves insulin sensitivity, and in patients with HALS, it may improve fat distribution." (PMID 40565151, 2025). "Localized lipodystrophy disorders are characterized by small amounts of subcutaneous fat loss from smaller areas of the body, and do not cause insulin resistance." (PMID 40565151, 2025). "Infusion site rotation was determined to be a feasible means of avoiding adverse lipodystrophy reactions, suggesting the need for proper patient education regarding appropriate insulin administration on an individual basis to maintain quality of life regardless of dermatologic complications." (PMID 39622650, 2024). "Moreover, myocardin serves as a key regulator of cardiac insulin sensitivity and metabolic homeostasis, highlighting myocardin as a potential therapeutic target for treating lipodystrophy- and diabetes-related cardiomyopathy." (PMID 38505620, 2024). "This case report aims to highlight the psychological implications of insulin-induced lipodystrophy." (PMID 39759721, 2024). "In conclusion, the psychological impact of insulin-induced lipodystrophy is often under-recognized." (PMID 39759721, 2024). "Lipodystrophy is a condition characterized by abnormal fat distribution at insulin injection sites." (PMID 39759721, 2024). "Compromised lipid homeostasis in Lal−/− mice, arising from impaired hepatic and intestinal lipid metabolism as well as lipodystrophy, leads to increased glucose consumption despite unaltered insulin levels, which ultimately results in reduced glucose concentrations in plasma and liver." (PMID 38160938, 2024). "Importantly, TZD treatment restored the insulin sensitivity of perigonadal fat, leading to a normal increase (2.78-fold) in the inguinal fat-dependence index of mice with partial lipodystrophy." (PMID 36835312, 2023). "Children and adolescents with lipodystrophy were four times more likely to have poor glycemic control than those without it; and those who came from families that cannot afford for insulin were six times more likely to have poor glycemic control than their counterparts." (PMID 35705956, 2022). "Interestingly, these authors also showed that the heart-specific deletion of seipin does not lead to any cardiac dysfunction, supporting that cardiomyopathy is a consequence of lipodystrophy and the subsequent insulin resistance." (PMID 35054926, 2022). "Adverse effects like lipodystrophy are one of the clinical complications which may occur related to insulin injection and lead to insulin absorption problems, which ultimately can hinder first OGC." (PMID 36153485, 2022). "Lipodystrophy may affect insulin absorption in skin areas involved, resulting in negative impact on blood glucose levels and glycemic variability." (PMID 35884071, 2022). "Lipodystrophy still represents a common complication in patients on insulin therapy." (PMID 35884071, 2022). "Children with lipodystrophy may need multiple injectable treatments including both insulin and metreleptin." (PMID 31434462, 2020). "The association of lipodystrophy with non-communicable disease, especially atherosclerosis, is due to lipodystrophy’s negative effects on lipids and insulin sensitivity, and pro-inflammatory effects on endothelial cells." (PMID 29945584, 2018). "We have recently shown that metreleptin improves not only insulin sensitivity, but also insulin secretion in patients with lipodystrophies, which could result from decreased lipotoxicity in pancreatic islets." (PMID 29578370, 2018).
lipodystrophy (continued). "Considering the interaction between lipodystrophy and insulin sensitivity in HIV+ persons, OGTT could be a useful DM diagnostic tool in subjects with abnormal fat distribution." (PMID 27066296, 2016). "Testosterone role in insulin sensitivity in HIV-lipodystrophy has also been proposed since several studies have shown that low levels of serum testosterone correlate not only with central fat accumulation but also with higher insulin levels." (PMID 27809804, 2016). "In this regard, we did not have data on some extra factors that may have an influence on lipid levels and insulin resistance, such as exercise habits, diet, lipodystrophy, and alcohol intake." (PMID 25367448, 2014). "In this regard, we did not have data on some extra factors that may influence on lipid levels and insulin resistance such as exercise habits, diet, lipodystrophy, and alcohol intake." (PMID 25159899, 2014). "For example, a mutation in PKB beta has been found to associate with severe IR and lipodystrophy, demonstrating the importance of the IRS-PI3K-PKB pathway to insulin sensitivity, although mutations in this protein appear to contribute to only a very small fraction of IR in the population." (PMID 23468892, 2013). "Indeed, there is evidence of insulin signaling cross-talk between the liver and adipose tissue with complete IR ablation specifically in adipose tissue, leading to lipodystrophy coupled with severe hepatic lipid accumulation and dysregulation of gluconeogenesis." (PMID 32350271, 2020). "Consequently, although reducing the intraregional variability in insulin absorption due to a reduced number of injections, the use of insulin pumps may increase the incidence of lipodystrophy due to reduced capacity to rotate injection sites." (PMID 30116732, 2018). "In addition, Trpm6-deficient animals developed signs of catabolic metabolism such as lipodystrophy, increased insulin sensitivity and hypothermia, and showed suppression of the somatotropic axis accompanied by induction of xenobiotic detoxification gene networks in the liver." (PMID 27991852, 2016). "These insulin-sensitizing and fat-inducingeffects of glitazones have lead to several clinical trials examining whether thesedrugs could reverse lipoatrophy andinsulin resistance in patients with HAART-associated lipodystrophy." (PMID 19096512, 2009). "In this model of lipodystrophy, an FGF21 analog, LY2405319, improved insulin sensitivity in young mice housed at 22°C." (PMID 40663389, 2025). "Both “Lipodystrophy 1” and “Lipodystrophy 2“ included PPARG among the top-weighted genes, which is known for its role in adipose tissue differentiation and as target of the insulin sensitizing thiazolidinediones." (PMID 39278900, 2024). "For example, the Lipodystrophy 1 and 2 clusters included rs17036160 near PPARG, the target of thiazolidinediones, which promote insulin sensitivity." (PMID 37886436, 2023). "Compared to the other groups, the lipodystrophy group had elevated GLC, TC, TG, ALT, AST, insulin (and consequently HOMA-IR and AT-IR), whereas HDL-C and LDL-C were decreased." (PMID 35279219, 2022). "With recovery of the lipodystrophy, adipose tissue mass, especially that of VAT and IHL, rises, but insulin resistance is lessened." (PMID 36176462, 2022). "In this review, we discuss how mouse models of inherited lipodystrophy have demonstrated the central role of white AT (WAT) in energetic homeostasis in general, including insulin sensitivity and lipid handling in particular." (PMID 35250856, 2022). "TT was significantly higher in the insulin signaling group and idiopathic SIR group than the lipodystrophy group (Kruskal–Wallis test followed by pairwise Wilcoxon rank sum test with Bonferroni correction, P < .005)." (PMID 33901270, 2021).